ELAVL4 (ELAV like RNA binding protein 4)
Diseases named in the same sentence as ELAVL4 in open-access papers:
ELAVL4 is named in the same sentence as 85 diseases in open-access papers, as found by Europe PMC text mining. Sharing a sentence is not in itself a finding about the gene and the disease. The quoted sentences say what the papers report.
neuroblastoma (18 papers, 2007 to 2026). Neuroblastoma (NB) is the most common solid, extracranial childhood tumor. "To this end, we have investigated two RNA-binding proteins (RBPs), previously reported to control MYCN expression in neuroblastoma, ELAVL4 (HuD) and IGF2BP1." (PMID 34026620, 2021). "Whereas ELAVL4 expression is decreased in MNA neuroblastoma, IGF2BP1 expression is elevated." (PMID 34026620, 2021). "Neuronal-origin HuD (ELAVL4) is an RNA binding protein overexpressed in neuroblastoma (NB) and certain other cancers." (PMID 35012594, 2022). "The RNA binding protein HuD (ELAVL4) is upregulated in a number of cancer types, particularly neuroblastoma (NB) and small cell lung cancer (SCLC), and its function in these cancers has not been well characterized." (PMID 35012594, 2022). "Also, by binding with a structure containing an AU-rich sequence, ELAVL2 and ELAVL4 together inhibit the assembly of the core complex of telomerase to reduce its activity and cell growth in human neuroblastoma cells; notably, the activity of this complex antagonizes the function of ELAVL1." (PMID 35465324, 2022). "However, ELAVL4 mRNA expression is significantly downregulated in MNA neuroblastoma." (PMID 34026620, 2021). "Among them, ELAVL4 received the most attention in SCLC, because it was found to be expressed in 100% of SCLC cells and more than 50% of neuroblastoma cells, and treatment targeting ELAVL4 can reduce tumor progression in nude mouse models." (PMID 35465324, 2022). "This is consistent with the reported role of ELAVL4 in antagonizing downregulation of MYCN expression by miR-17 and recently reported roles in the 3’UTR-dependent enhancement of mRNA translation in neural and neuroblastoma-derived cells." (PMID 34026620, 2021). "Finally, we evaluate if trans-acting factors, in particular IGF2BP1 and ELAVL4, or a putative miRNA decoy function of the MYCN-3’UTR uncouple increased expression of MYCN-regulatory miRNAs in neuroblastoma from elevated expression of MYCN protein." (PMID 34026620, 2021).
small cell lung carcinoma (12 papers, 2009 to 2024). Small cell lung cancer (SCLC) is a highly aggressive malignant neoplasm, accounting for 10-15% of lung cancer cases, characterized byrapid growth, and early metastasis. "The neuron-specific RNA binding protein Hu Antigen D (HuD) (also known as Embryonic Lethal, Abnormal Vision, Drosophila Like RNA Binding Protein 4 (ELAVL4)) is overexpressed in a number of cancer types, notably NB and small cell lung cancer." (PMID 35012594, 2022). "Subacute sensory neuropathy/encephalomyelopathy syndrome (Hu syndrome) is characterized by a high-titer antibody response to the tumor nerve antigen HuD (also known as ELAVL4), which is usually expressed only in neurons and small cell lung cancer (SCLC)." (PMID 35294333, 2022).
Parkinson disease (11 papers, 2011 to 2024). A progressive degenerative disorder of the central nervous system characterized by loss of dopamine producing neurons in the substantia nigra and the presence of Lewy bodies in the substantia nigra and locus coeruleus. "The ELAVL4 gene is known to be associated with hallucinogen abuse, paraneoplastic neurologic disorders, and Parkinson disease." (PMID 28957450, 2017). "Furthermore, genetic variants in human ELAVL4 gene have been associated with age of onset in Parkinson’s disease (PD)." (PMID 28283027, 2017). "In addition, genetic variants in human ELAVL4 have been associated with age of onset in Parkinson disease (PD)." (PMID 28283027, 2017). "Indeed, recent studies implicate ELAVL4 as a Parkinson's disease susceptibility gene." (PMID 21674006, 2011). "Several studies have shown that ELAVL4 involved in the pathogenesis of neurodegenerative diseases, such as Alzheimer’s disease, Parkinson’s disease, and amyotrophic lateral sclerosis." (PMID 35677353, 2022).
Alzheimer disease (10 papers, 2017 to 2025). A progressive, neurodegenerative disease characterized by loss of function and death of nerve cells in several areas of the brain leading to loss of cognitive function such as memory and language. "Elavl3 is essential for cerebellar function and has been associated with epilepsy, while Elavl4 is linked to neurodegenerative diseases, including Parkinson’s and Alzheimer’s diseases." (PMID 40000387, 2025). "A new study revealed that ELAVL4 influences multiple biological pathways linked to Alzheimer’s disease, including those involved in synaptic function and the expression of genes downstream of APP and tau signaling." (PMID 38632655, 2024).
lung carcinoma (10 papers, 2012 to 2025). "UCHL1 participates in the early transformation and tumorigenesis of lung epithelial cells, and serum ELAVL4 levels are significantly higher in patients with lung cancer, indicating their diagnostic relevance." (PMID 39661479, 2025).
amyotrophic lateral sclerosis (6 papers, 2018 to 2024). Amyotrophic lateral sclerosis (ALS) is a neurodegenerative disease characterized by progressive muscular paralysis reflecting degeneration of motor neurons in the primary motor cortex, corticospinal tracts, brainstem and spinal cord. "For example, ELAVL2 has been linked to learning and memory formation, autism spectrum disorder and schizophrenia; ELAVL3 has been linked to amyotrophic lateral sclerosis (ALS) and cerebellar ataxia; ELAVL4 has been linked to AD and PD." (PMID 39425207, 2024).
schizophrenia (5 papers, 2011 to 2024). A major psychotic disorder characterized by abnormalities in the perception or expression of reality. "Noteworthy, the altered expression of GAP43, one of known targets of ELAVL4, is reported in the frontal cortices and the hippocampus of patients with schizophrenia." (PMID 21674006, 2011). "Defects in ELAVL2/HuB, ELAVL4/HuD, and their target transcripts can lead to abnormal neuronal proliferation and development and result in the pathogenesis of numerous CNS disorders, including seizures, autism, and schizophrenia." (PMID 36438188, 2022).
epilepsy (4 papers, 2013 to 2025). A brain disorder characterized by episodes of abnormally increased neuronal discharge resulting in transient episodes of sensory or motor neurological dysfunction, or psychic dysfunction. "This correlates with our observation that NOVA haploinsufficiency is sufficient to induce spontaneous epilepsy, an observation also made with the neuronal RNABP Elavl3 and Elavl4." (PMID 23359859, 2013). "Interestingly, we observed that when compared to the normal controls, the expression of some identified genes was only significantly altered either in Epilepsy (EGLN1, ELAVL4, and NFE2l2) or Hemorrhage (USP22, EYA1, SIX1, OAS3, SRMS) groups." (PMID 34588521, 2021). "Interestingly, downregulation of EGLN1, ELAVL4, NFE2L2 KCNK18 genes was only detected in epilepsy-related (CvsE) gene list." (PMID 34588521, 2021).
paraneoplastic neurological syndrome (4 papers, 2009 to 2023). "The human family of four ELAV-like (ELAVL) genes were first identified starting with ELAVL4/HuD, which was recognised as a target antigen of paraneoplastic neurological syndrome (anti-Hu syndrome)." (PMID 37697079, 2023).
depression (3 papers, 2018 to 2025). "In addition to GRM5, ELAVL4, implicated in depression and in epigenome-wide association studies of suicide, was significant in females, but not males." (PMID 36750733, 2023). "Nevertheless, ELAVL4 and its concurrent downstream alterations remain elusive regarding its relationship to depression." (PMID 39940881, 2025). "Previous studies have identified ELAVL4 as an RBP targeting several neuroplasticity-related mRNAs, including Bdnf, Ngf, Gap-43, and Nrn1, all of which are closely associated with neuroplasticity and have well-established links to depression." (PMID 39940881, 2025). "Moreover, our study extends this understanding to depression, highlighting ELAVL4 as a potential key protein in resveratrol’s antidepressant action on neuroplasticity." (PMID 39940881, 2025). "Overall, this research sheds light on the role of the ELAVL4-Bdnf mRNA pathway through neuroplasticity in resveratrol’s antidepressant action, which provides an mRNA regulation perspective for the development of novel antidepressants and understanding depression pathology." (PMID 39940881, 2025).
ovarian carcinoma (3 papers, 2009 to 2024). A malignant neoplasm originating from the surface ovarian epithelium. "Furthermore, it was recently reported that ELAVL2 and ELAVL4 activated glycolysis pathway under glucose deprivation condition and their high expression levels were responsible for the development of chemoresistance to paclitaxel in ovarian cancer cells." (PMID 38548861, 2024).
gastric cancer (2 papers, 2016 to 2025). A primary or metastatic malignant neoplasm involving the stomach. "Elavl4 is considered a potential oncogene in glioblastoma because it stabilizes pro-survival mRNAs, while HuR (Elavl1) promotes tumour progression in hepatocellular carcinoma and gastric cancer, with its high cytoplasmic expression linked to poor prognosis." (PMID 40000387, 2025).
memory impairment (2 papers, 2021 to 2024). "Reducing EV secretion, interfering with miR-142-5p expression or overexpressing ACTN4, ELAVL4 and USP9X ameliorated memory impairment and rescued CNP-associated dendritic spine changes." (PMID 38632655, 2024). "miR-142-5p was identified as the key molecule responsible for pathological SC-EVs-mediated memory impairment, and α-actinin-4 (ACTN4), ELAV-like protein 4 (ELAVL4, also known as HuD) and ubiquitin-specific peptidase 9 X-linked (USP9X) were identified as novel target molecules of miR-142-5p." (PMID 38632655, 2024).
motor neuron disease (2 papers, 2018 to 2021). "ELAVL4 has also been shown to be involved in spinal muscular atrophy, another motor neuron disorder." (PMID 34618203, 2021).
Obesity (2 papers, 2016 to 2020). Accumulation of substantial excess body fat. "We observe significant associations of adiposity-OTU abundances with host genetic variants in the FHIT, TDRG1 and ELAVL4 genes, suggesting a potential role for host genes to mediate the link between the fecal microbiome and obesity." (PMID 27666579, 2016). "Genetic variants in several genes, including SLC9A2, ELAVL4 and LINGO2, are associated with both obesity and Blautia abundance, which could suggest that the mechanism of these variants acts through the gut microbiome." (PMID 32580458, 2020).
Autoimmunity (1 paper, 2022). The occurrence of an immune reaction against the organism's own cells or tissues. "Hence, such TAA-AAbs may be successfully used for various diagnostic purposes in general oncology apart from the clinical context of the cancer-associated autoimmunity, as exemplified by HuD/ELAVL4 antigen representing one of seven TAAs in the EarlyCDT®-Lung panel (see Section 3.2)." (PMID 35203677, 2022).
deafness (1 paper, 2022). An inherited or acquired condition characterized by the complete loss of the ability to hear from one or both ears. "Genes already associated with hearing or deafness (mouse and/or zebrafish) were selected as controls/references for comparison and validation of the candidate genes’ results: Eya4 (DFNA10), Gsdmea (DFNA5), Gsdmeb (DFNA5), Pou4f1, Elavl4, Sclla3a, Gab1 (DFNB26), and Mettl1 (DFNM)." (PMID 36553541, 2022).
ischemic stroke (1 paper, 2022). A stroke disorder caused by obstruction of blood flow to the brain, due to thrombotic (local blood clot formation) or embolic (due to a blood clot or other material traveling from another site) event. "However, whether ELAVL4 is involved in the pathogenesis of ischemic stroke remains unclear." (PMID 35677353, 2022).
mammary tumor (1 paper, 2023). "In this study, we found that lncRNA34977 promoted the proliferation, migration and invasion of canine mammary tumors and inhibited their apoptosis by regulating the expression of miR-8881/ELAVL4." (PMID 36604379, 2023). "The main objective of this study was to assess the potential impacts of lncRNA34977 on the development of canine mammary tumors by regulating the expression of miR-8881/ELAVL4 and thus provides a new avenue for the treatment of canine mammary tumors." (PMID 36604379, 2023). "The aim of this study was to investigate the effects of lncRNA34977 on the proliferation, migration, invasion, and apoptosis of canine mammary tumor (CMT) cells through the regulation of miR-8881/ELAVL4 expression." (PMID 36604379, 2023).
non-small cell lung carcinoma (1 paper, 2019). A group of at least three distinct histological types of lung cancer, including non-small cell squamous cell carcinoma, adenocarcinoma, and large cell carcinoma. "On the other hand, ELAV-like RNA binding protein 4 (ELAVL4) has been shown to modulate radiation sensitivity in vitro in non-small cell lung cancer." (PMID 30626092, 2019).
pancreatic neuroendocrine tumor (1 paper, 2022). Pancreatic endocrine tumor, also known as pancreatic neuroendocrine tumor (PNET), describes a group of endocrine tumors originating in the pancreas that are usually indolent and benign, but may have the potential to be malignant. "ELAVL4 has also been shown to interact with both the 3′-UTR and 5′-UTR regions of the p27 mRNA to promote its translation leading to tumor suppression, but ELAVL4 and p27 levels are both reduced in pancreatic neuroendocrine tumors." (PMID 35465324, 2022).
tumor (29 papers, 2009 to 2025). "Despite lacking protein-coding potential, RBPmap analysis identified binding sites for key RNA-binding proteins (RBPs) implicated in GBM, including IGF2BP, ELAVL4, and MSI1, which regulate processes such as RNA splicing, stability, and tumor cell self-renewal." (PMID 40076844, 2025). "UCHL1 and ELAVL4, the “old” TAAs, are well-recognized biomarkers involved in deubiquitination and RNA translation processes, both of which contribute to tumor cell proliferation and survival." (PMID 39661479, 2025). "As the antigen target of autoreactive CD4+ T cells, ELAVL4 may directly participate in cell-mediated anti-tumor immunity and nervous system damage." (PMID 35465324, 2022). "In contrast, at relapse, the phenotype of tumor cells shifted drastically, with only CD56, GATA-3 and ELAVL4 expression being retained, albeit with high variance at the single-cell level." (PMID 40753395, 2025). "Our study found that the expression of ELAVL1 was significantly high in tumor samples, while that of other three members (ELAVL2, ELAVL3 and ELAVL4) was significantly low in tumors." (PMID 28035070, 2017).
cancer (21 papers, 2009 to 2025). A tumor composed of atypical neoplastic, often pleomorphic cells that invade other tissues. "In GBM scenario, we hypothesize that downregulation of ELAVL2, ELAVL3 and ELAVL4 may be preferred to further enhance the translation of HuR, leading to a less differentiated and highly proliferative state of cancer cells." (PMID 28035070, 2017).
neurodegenerative disease (11 papers, 2020 to 2025). A disorder of the central nervous system characterized by gradual and progressive loss of neural tissue and neurologic function. "Taken together, ELAVL4 is linked to the pathogenesis of neurodegenerative diseases, including AD, and could possibly be a therapeutic target for AD." (PMID 33324198, 2020). "Adenylate/urydilate-rich elements bind transcription factors such as ELAVL4 (HuD), a member of the ELAVL family, required for neuronal differentiation and strongly associated with neurodegenerative diseases." (PMID 40725035, 2025). "They primarily involved mechanisms well-established in neurodegenerative diseases, such as synaptic dysfunction and protein misfolding, and with shared directionality of changes for the genes involved, such as ELAVL4 and DNAJB6 (upper part)." (PMID 41318503, 2025). "In summary, Elavl4 binds to target mRNAs to promote neuronal maturation and function, and it may contribute to neurodegenerative diseases through its regulation of mRNA stability." (PMID 40000387, 2025).
nervous system diseases (8 papers, 2011 to 2025). "The main goal of this review is to provide an updated overview of the involvement of the RNA-binding protein (RBP) HuD, encoded by the ELAVL4 gene, in nervous system development, maintenance, and function, and its emerging role in nervous system diseases." (PMID 36498933, 2022).
ELAVL4 also shares sentences with these, for which no sentence is quoted: diabetes (11 papers); insulinoma (6); Cognitive impairment (4); neuropathy (3); psychiatric disease (3); type 2 diabetes mellitus (3); autism (2); cerebellar degeneration (2); encephalomyelitis (2); glial tumours (2); glioblastoma (2); gynecological cancer (2); Hyperglycemia (2); Parkinson’s (2); spinal muscular atrophy (2); Stroke (2); acute lymphoblastic leukemia (1); alcohol dependence (1); amnestic disorder (1); anxiety disorder (1); autism spectrum disorder (1); autoimmune disease (1); autoimmune encephalitis (1); bipolar disorder (1); brain tumors (1); cerebellar ataxia (1); cognitive disorder (1); Crohn disease (1); developmental delay (1); diabetic neuropathy (1).
A further 30 diseases each share a sentence with ELAVL4 in 1 paper.